C3 (complement C3)
Diseases named in the same sentence as C3 in open-access papers (continued):
Sharing a sentence is not in itself a finding about the gene and the disease.
Insulin resistance (53 papers, 2008 to 2026). Increased resistance towards insulin, that is, diminished effectiveness of insulin in reducing blood glucose levels. "C1q, C3 and C4 are also associated with Wnt signalling, metabolic disorders, and insulin resistance pathways found in our ORA of PaM DEGs, or cholesterol metabolism found in our ORA of PaM astrocytes DEGs." (PMID 39954093, 2025). "Elevated concentrations of C3, an acute-phase response protein, have been shown to be correlated with insulin, glucose, insulin resistance and associated with an increased risk of type 2 diabetes." (PMID 37658860, 2023). "There was an association between C1q, C3, C4, and FH and β-pancreas cell function, whereas only FH was associated with insulin resistance." (PMID 35370615, 2022). "We noticed that insulin resistance is strongly associated with serum exosomal C3 levels of GDM pregnancies." (PMID 36080270, 2022). "C3 and C4 are expressed and secreted by adipose tissue, and serum C3 is strongly associated with components of metabolic syndrome, such as insulin resistance, lipid profile, and BMI." (PMID 32878271, 2020). "Previous studies have shown that complement C3 and immunoglobulin E levels have strong associations with insulin resistance and abdominal obesity in the young and middle-aged populations." (PMID 30454064, 2018). "Complement C3 and immunoglobulin E levels have been strongly associated with insulin resistance and abdominal obesity in the elderly." (PMID 30454064, 2018). "Nick Wlazlo revealed that Complement C3 (C3) were longitudinally associated with insulin resistance in type 2 diabetes over a 7-year follow-up period, and may reflect progression of metabolic dysregulation." (PMID 36064366, 2022). "However, C3 mRNA levels were more associated with insulin resistance, and positive correlations with insulin, glucose and homeostasis model assessment-estimated insulin resistance (HOMA-IR) existed." (PMID 30104553, 2018). "The treatment was accompanied by a decrease in complement component 3 (C3), the mediator that promotes insulin resistance and inflammation." (PMID 40004134, 2025). "This response was associated with an improvement in insulin resistance coupled with a decrease in acute-phase proteins like hs-CRP, C3 protein, and PAI-1." (PMID 38539836, 2024). "Serum complement C3 was reported to have a stronger link with insulin resistance than with high-sensitivity C-reactive protein (hsCRP) in PCOS women." (PMID 36980195, 2023). "For instance, C3, factor B, and factor D activate the alternative pathway, leading to the generation of anaphylatoxins C3a and C5a, which induce insulin resistance and disrupt lipid metabolism in the liver." (PMID 38155961, 2023). "Higher expression of the complement 3 (C3) gene has been demonstrated in individuals with insulin resistance or hyperinsulinemia." (PMID 36837780, 2023). "In contrast, C3 plays a central role in activation of the complement system and can be used as a biomarker for insulin resistance and cardiometabolic diseases." (PMID 35240026, 2022). "Complement factor C3 has been studied, particularly in the setting of obesity-induced insulin resistance because of its cleavage product, C3adesArg, which is also termed acylation-stimulating protein (ASP)." (PMID 36293087, 2022). "On the other hand, C3 mRNA levels were related to insulin resistance and glucose homeostasis, which is in line with previous results from our group and from other authors." (PMID 30104553, 2018). "This response was associated with an improvement in lipoprotein profile and insulin resistance, coupled with a decrease in acute-phase inflammatory proteins, such as hs-CRP and C3, and a reduction in levels of pro-atherosclerotic molecules, such as PAI-1 and ICAM-1." (PMID 39061938, 2024).
Insulin resistance (continued). "For the two proteins that differed in women with PCOS versus control women (complement C3 and alpha-1-antitrypsin), correlations with age, BMI, insulin resistance (HOMA-IR), testosterone and circulating levels of TG, cholesterol, HDL-C, LDL-C and CRP were performed." (PMID 37181037, 2023). "Increased complement factor proteins in PCOS have been reported for both the classical and alternate cascade pathways, including C3, C4, properdin, factor B, and factor D, though their expression and activation appeared to be dependent upon obesity and insulin resistance." (PMID 36619572, 2022). "C3, Saa1 and Saa3, which is regulated by S100a8, encode secretory proteins that can excrete from adipocytes into the local environment, leading to the enhanced inflammation in WAT and insulin resistance." (PMID 31614949, 2019). "Intact C3 and C5 proteins and the cleaved C3a and C5a peptides are reported to act as mediators of inflammation-induced insulin resistance, but a beneficial effect of complement factor D, a protease required for the generation of the C3 convertase, on β-cell function has been demonstrated." (PMID 28921001, 2018). "In a prospective study, fibrinogen, complement C3, C4 and haptoglobin were associated with insulin resistance and incident type 2 diabetes, but not α1-antitrypsin, ceruloplasmin or orosomucoid." (PMID 29258604, 2017). "Among these markers, serum complement C3 is strongly associated with insulin resistance, independent of the components of metabolic syndrome." (PMID 29299442, 2017). "In this study we aimed to investigate whether insulin resistance induced by a high-fat diet might influence the complement system, and particularly circulating C3 level and complement activation." (PMID 28450702, 2017). "We hypothesized that our short term HFO challenge would increase serum level of C3 and induce complement activation possibly affecting the development of insulin resistance." (PMID 28450702, 2017). "In addition to insulin resistance, other components of metabolic syndrome are also related to complement C3." (PMID 29299442, 2017). "Notably, serum complement C3 was shown to have a stronger association with insulin resistance than highly sensitive C-reactive protein in non-diabetic Chinese patients." (PMID 35610262, 2022). "In addition, systemic levels of complement C3 and C4 have been shown to be higher in patients with metabolic syndrome, and C1q expression has been reported to be dysregulated in adipocytes during insulin resistance, which also occurs in cachexia." (PMID 34830921, 2021). "Compelling preclinical evidence established a role of adipose-tissue C3 and its cleavage products on acylation stimulating protein (ASP) in adipose tissue inflammation, insulin resistance and cardiometabolic diseases." (PMID 37484967, 2023). "In the present study, we reveal a significant relationship between the elevated complement proteins C1q, C3, C4, and FH and enhanced β-cell function (HOMA-β) and insulin resistance (HOMA-IR)." (PMID 35370615, 2022). "GDM is a pro-inflammatory state as evidenced by raised C-reactive protein (CRP) levels; increased oxidative stress is found in GDM, secondary to insulin resistance, leading to lower CFH and higher C3 levels." (PMID 35628864, 2022). "Viewing all individuals circulating levels of C4, C3, C3bc, TCC and complement activation capacity decreased paradoxically along the development of insulin resistance after HFO (P = 0.0015, P < 0.0001, P = 0.01, P < 0.0001, P = 0.0002, P < 0.0001, P = 0.0006)." (PMID 28450702, 2017). "Furthermore, fasting circulating complement components, such as C3 and C3a (desArg), are higher in PCOS women with insulin resistance, which increases to a similar extent in the control and PCOS groups." (PMID 40904461, 2025). "This also suggests that increased insulin resistance is mediated by complement C3 rather than complement C3, being an epiphenomenon of inflammation." (PMID 36980195, 2023).
Insulin resistance (continued). "As mentioned in our study, complement C3 and serum insulin concentrations and insulin resistance were higher in NWO than those in non-NWO subjects." (PMID 29299442, 2017).
age-related macular degeneration (52 papers, 2008 to 2026). Age-related loss of vision in the central portion of the retina (macula), secondary to retinal degeneration. "The loss of this salt bridge in the C3F allotype is associated with age-related macular degeneration, leading to deposition of complement C3 in drusen, and with atypical hemolytic uraemic syndrome, leading to endothelial tissue damage in the kidneys." (PMID 25488663, 2015). "Genetic variants in the complement component 3 gene (C3) have been shown to be associated with age-related macular degeneration (AMD) in Caucasian populations of European descent." (PMID 22174912, 2011). "Next generation sequencing (NGS) showed polymorphism in CFH (p.V62I in SCR1) and THBD (p.A473V) already known as pathogenic for C3GN, as well as a mutation in C3 (p.R102G) associated only with age-related macular degeneration (AMD) so far." (PMID 29592796, 2018). "Pegcetacoplan, a complement component 3 (C3) inhibitor, has recently received U.S. Food and Drug Administration approval for treating geographic atrophy (GA), an advanced stage of age-related macular degeneration (AMD)." (PMID 41347874, 2025). "CFH accelerates the alternative C3 convertase through competitive binding with C3b and its inadequate recognition of cells can cause conditions such as atypical hemolytic uremic syndrome (aHUS), age-related macular degeneration (ARMD), and membrano-proliferative glomerulonephritis type II." (PMID 41356214, 2025). "The C3 inhibitor CP-40 tested here, is a small peptide analog of the Compstatin family, which is currently under clinical development for the treatment of age-related macular degeneration." (PMID 34691058, 2021). "We found the two common C3 polymorphisms in many of both the patients and controls; R102G and P314L, which both have been associated with age-related macular degeneration (AMD) in many studies." (PMID 30131807, 2018). "Indeed, genes in the complement pathway, including complement factor H (CFH), C2/BF, and C3, are known to be associated with age-related macular degeneration (AMD)." (PMID 27748412, 2016). "Complement activation products such as C3 have been shown to be present in the eyes of patients with autoimmune uveitis and in drusen in patients with age-related macular degeneration." (PMID 21031137, 2010). "A large number of studies have shown that C3 and its lysates may promote the occurrence and development of age-related macular degeneration." (PMID 36249739, 2022). "In genetic studies on age-related macular degeneration (AMD), its association with the CFH gene led to the discovery that other molecules in the complement pathway were also associated with the condition, such as C2/CFB, C3, and CFI." (PMID 23213273, 2012). "The CD subtype of AMD was significantly associated with current smoking as well as variants in the complement factor H (CFH), age-related maculopathy susceptibility 2 (ARMS2), complement factor B/complement component 2 (CFB/C2), complement component 3 (C3), and apolipoprotein E (APOE) genes." (PMID 22933840, 2012). "For example, in age-related macular degeneration (AMD), a retinal disease clinically and pathologically linked to LOAD, genes encoding complement components C2, C3, FB and C9, and regulators FH and FHR4, all contribute to risk." (PMID 33804666, 2021). "Examples include an engineered human MTSP1 protease targeting C3 as a treatment of age-related macular degeneration (AMD) and the use of ScpA, a bacterial protease specific for C5a, as an intervention in sepsis." (PMID 33897974, 2021). "It has been shown that the activity of the complement system is strongly associated with the development of neovascular age-related macular degeneration, and that complement 2, complement 3 (C3) and complement 5 proteins play a major role in the classical complement pathway and pathogenesis of AMD." (PMID 39867928, 2024).
age-related macular degeneration (continued). "Drugs targeting the complement system, such as monoclonal AB against C3 or C5, have been tested in several clinical trials (phase II and III) for various diseases, including age-related macular degeneration." (PMID 34943212, 2021). "In models of age-related macular degeneration (AMD), C3-expressing microglia and complement deposited proteins colocalized to lesions of photo-oxidative damage perpetrating neurodegeneration and intravitreal injection of C3 small interfering RNA (siRNA) prevented neurodegeneration." (PMID 36517889, 2022). "The C3 blocker compstatin, administered intravitreally in nonhuman primates, has shown a reversal of drusen formation by suppression of complement activation in age-related macular degeneration (AMD)." (PMID 36362117, 2022).
acute kidney injury (48 papers, 2010 to 2026). Sudden and sustained deterioration of the kidney function characterized by decreased glomerular filtration rate, increased serum creatinine or oliguria. "The risk of renal failure increased as C3 levels in kidney biopsy samples increased in a previous study using multivariate logistic regression." (PMID 38260086, 2023). "Among the traditional immunological biomarkers, low levels of C3 have been shown to be a risk factor for renal failure within 20 years (RRadj = 2.0; p = 0.01) in a large cohort of SLE patients." (PMID 36233628, 2022). "In these models initial podocyte injury (either induced by Adriamycin or protein overload) resulted in glomerular C3 deposition, podocyte injury and loss, proteinuria, glomerular sclerosis, tubulo-interstitial fibrosis and acute kidney injury." (PMID 32447506, 2020). "In our patient, however, the presence of C1q and C3 strong mesangial deposition in the glomerulus examined supports the evidence of autoimmune nephritis as the cause of the renal failure." (PMID 21197407, 2010). "Additionally, the levels of serum C3 deposition in glomeruli are positively correlated with the risk of renal failure." (PMID 37781380, 2023). "Levels of C3 deposition in glomeruli positively correlate with risk of renal failure." (PMID 37781380, 2023). "In this report, we present a unique case of acute kidney injury (AKI) in the setting of isolated C3 deficiency and a ruptured hemorrhagic ovarian cyst." (PMID 40995257, 2025). "IgA-DIRGN is characterized by diffuse endocapillary proliferation and the formation of mesangial deposits of IgA and C3, leading to inflammation and subsequently resulting in acute kidney injury, proteinuria, hematuria, and hypocomplementemia." (PMID 42232824, 2026). "Mice lacking local C3 synthesis were protected from tubular damage and renal failure despite normal circulating C3 levels." (PMID 40421273, 2025). "Glomerular C3 staining intensity has been found to correlate with proteinuria and extensive glomerular C3 deposition can serve as a predictor of renal failure in patients with MN." (PMID 40018357, 2025). "Previous studies have found that the intensity of glomerular C3 staining correlates with proteinuria and is a predictor of renal failure in patients with MN." (PMID 40018357, 2025). "In patients with evidence of acute kidney injury, C3 deposited in many of the injured tubules, whereas very high levels of complement activated fragments were found in plasma and urine of pediatric subjects." (PMID 35681450, 2022). "It was also characterized by nephrotic range proteinuria in 80% of patients, C3 consumption in 67%, and dialysis-requiring renal failure in 40%." (PMID 34714369, 2022). "For example, Met-111 and Met-147 of serum albumin showed far lower baseline [Met(O)]/[Met] than Met-1181 of complement C3, but these residues were clearly more oxidized in patients with type 2 diabetes and renal failure." (PMID 27929071, 2016). "Others have suggested that for IgAN, the C3/C4 ratio may be a better marker for disease activity and predictor of renal failure than sC3 levels alone." (PMID 38731122, 2024). "We speculate, that it is most likely caused by additional complications in the ICU patients, such as renal failure, severe pneumonia, or embolism, as well as an exhausted immune response with complement consumption (declining C3, C4, AP and CP activity, as also shown in our previous publication." (PMID 37051252, 2023). "The fact that glomeruli C3 deposits preceded electron dense deposits and MPGN‐like changes suggests that the dysregulated AP precipitated the eventual renal failure." (PMID 36203396, 2023). "Complement C3 plays a prominent role in inflammatory processes, and its increase exacerbates ischemia reperfusion injury (IRI)-induced acute kidney injury (AKI)." (PMID 35250972, 2022).
acute kidney injury (continued). "Multiple studies describe that patients with acute kidney injury induced by iTTP have lower serum levels of C3 than patients with iTTP without acute kidney injury during the acute period." (PMID 39185293, 2024). "A renal biopsy pursued in the etiological investigation of this non-oliguric acute kidney injury revealed a single subepithelial electron-dense deposit and granular immunofluorescent C3 staining in peripheral mesangial segments." (PMID 35935112, 2022). "Notably, hematuria (P = 0.035), leukocyturia (P = 0.002), and acute kidney injury (P = 0.001) were more frequent in TBM C4d-positive patients, who also had higher levels of urinary protein, Scr, and SLEDAI value, and a lower serum C3 value." (PMID 34276649, 2021). "Release of many cytokines, including IL-1, IL-6, IL-8, IL 10, complement C3/C4, and tumor necrosis factor-α PCT, Leucocytes are characteristic of the inflammation and contribute to postoperative acute kidney injury (AKI)." (PMID 38888547, 2024). "In the HUS cohort, lastly, association analyses revealed that the risk of developing renal failure could not be predicted on the basis of age, sex, serum measurements (including LDH and C3 levels), and etiology (not shown)." (PMID 34714369, 2022).